FAM167A-AS1 (FAM167A antisense RNA 1)
Synonyms: C8orf12
Gene: Long non-coding RNA gene on chromosome 8 (11,368,402 to 11,438,658, forward strand). Ensembl gene ENSG00000184608.
Diseases named in the same sentence as FAM167A-AS1 in open-access papers:
FAM167A-AS1 is named in the same sentence as 1 disease in open-access papers, as found by Europe PMC text mining. Sharing a sentence is not in itself a finding about the gene and the disease.
FAM167A-AS1 shares sentences with these, for which no sentence is quoted: Tinnitus (1 paper).